RNU4-57P (RNA, U4 small nuclear 57, pseudogene)
Gene: Small nuclear RNA gene on chromosome 1 (223,373,822 to 223,373,956, forward strand). Ensembl gene ENSG00000251789.
Homologues: Orthologues: chimpanzee U4 (76% identical), dog U4 (57% identical), dog U4 (56% identical), mouse Gm54493 (47% identical), guinea pig U4 (42% identical). Paralogues in human: RNU4-55P (57% identical), RNU4-82P (57% identical), RNU4-48P (56% identical), RNU4-74P (56% identical), RNU4-22P (53% identical), RNU4-29P (53% identical), RNU4-77P (53% identical), RNU4-75P (53% identical), RNU4-15P (52% identical), RNU4-54P (52% identical), RNU4-86P (52% identical), RNU4-91P (52% identical), and 81 more.